CXorf66 (chromosome X open reading frame 66)
Synonyms: RP11-35F15.2; SGPX
Tractability: Antibody: UniProt predicts a signal peptide or a membrane-spanning region.
Gene: Protein-coding gene on chromosome X (139,955,728 to 139,965,521, reverse strand). Ensembl gene ENSG00000203933.
Subcellular location: Membrane
Subcellular location (Human Protein Atlas): Annulus; Calyx; Perinuclear theca; End piece; Mid piece; Principal piece
Gene Ontology:
Molecular function: protein binding
Cellular component: membrane
Homologues: Orthologues: chimpanzee CXHXorf66 (98% identical), macaque CXHXorf66 (89% identical), dog CXHXorf66 (45% identical), rat Cxhxorf66 (32% identical), mouse Gm7073 (28% identical).